IL10 (interleukin 10)
Diseases named in the same sentence as IL10 in open-access papers (continued):
Sharing a sentence is not in itself a finding about the gene and the disease.
COVID-19 (continued). "Recent published studies in adult populations have reported that elevated levels of inflammatory cytokines levels such as TNF-α, IL-1β, IL-6, IL-10, IL-17, IL-18, IFN-γ are seen in active COVID-19 individuals compared to seropositive individuals and healthy controls." (PMID 33813138, 2021). "To ascertain if the therapeutic effect of Xanthohumol relieved virus-induced cytokine dysregulation, we determined the expression levels of IL-6, IL-10, and TNF-α, which are prognostic markers for severe COVID-19, as well as other major pro-inflammatory cytokines including IFN-γ." (PMID 34702802, 2021). "To investigate the role of cytokines and chemokines in the inflammatory status of COVID-19 and MIS-C, we measured plasma levels of IL-1ß, IL-2, IL-4, IL-5, IL-6, IL-10, TNF-α, IL-17A, IFN-α, IFN-γ, CXCL10/IP-10, CXCL8/IL-8, CXCL9/MIG, CCL5/RANTES, and CCL2/MCP1." (PMID 33841438, 2021). "Our severe COVID-19 patients also had significantly higher levels of IL-10 and IL-1Ra compared with non-severe patients, which was also shown in a previous report." (PMID 34367188, 2021). "The corresponding differences in endotypes consist in an early increase in blood IL-10 in symptomatic COVID-19 patients compared to no increase in symptomatic SARS." (PMID 33746948, 2021). "Last but not least, it is possible that IL-10 cooperates toward immunosuppression with other anti-inflammatory cytokines found increased in symptomatic COVID-19, such as IL-4, and IL-1RA." (PMID 33746948, 2021). "COVID-19 patients in the intensive care unit (ICU) have been reported to exhibit increased systemic levels of IL-10, as compared to non-ICU patients." (PMID 34646263, 2021). "The identified crucial cytokine panel, including IL6, IL1β, IL10, CXCL10, IGF1, and GALECTIN-1, may offer the selective targets to improve the efficacy of COVID-19 therapy." (PMID 34238338, 2021). "Our synthesized results revealed significantly lower levels of immune cells in CD3+ T, CD4+ T, CD8+ T, B and NK cells, higher levels of cytokines (TNF-α, IL-5, IL-6 and IL-10) and higher levels of chemokines (MCP-1, IP-10 and eotaxin) in severe cases compared with mild cases of COVID-19." (PMID 34344353, 2021). "In addition, COVID-19 group showed increased TNF-α level and decreased IL-2, IL-6, IL-10, and IFN-γ levels." (PMID 34667157, 2021). "In contrast, the expression of IL-10, a prototypical regulatory cytokine, was significantly increased in CD4+T cells from nonhospitalized patients after stimulation with M peptides when compared to the mild COVID-19 group (p = 0.035)." (PMID 34021148, 2021). "Our transcriptomic data suggest that compared to other types of ARDS, COVID-19 ARDS is characterized by increased PTEN, interferon-γ, and CNTF-stimulated gene expression juxtaposed against inhibition of genes typically activated by IL-10." (PMID 34446707, 2021). "On the contrary, taking into account anti-inflammatory cytokines, IL-1RA, IL-10, IL-27, and IL-19 were higher in COVID-19 pregnant women if compared with noninfected ones." (PMID 34326336, 2021). "Adverse events/severe adverse events, COVID-19 symptoms, SARS-Cov-2 virus test, blood SARS-Cov-2 IgM and IgG antibodies tests, blood cytokine and inflammatory (CRP, IL_6, IL-10, TNFα) tests and disease severity evaluation for 6 months after the last dose of AdMSC infusion for the SG and CG." (PMID 33815867, 2021). "Total T cells, and CD4+ and CD8+ T cell counts are negatively correlated with serum IL-6, IL-10, and TNF-α levels in COVID-19 patients, and patients in the disease resolution period exhibit decreased IL-6, IL-10, and TNF-α concentrations and restored T cell counts." (PMID 34818337, 2021). "When compared with controls, Eotaxin in men, and MCP-3 in women were significantly lower, and IL-10 in women was higher, a control vs. COVID-19 difference that was not seen in the counterpart sex, respectively." (PMID 34930441, 2021).
COVID-19 (continued). "When we compared historical and present control subjects who had normal cognition (no viral illness), we found that patients with COVID-19 and neurologic symptoms had increased CSF levels of IL-6, IL-8, IL-10, IP-10, and TNF-α." (PMID 32487282, 2020). "Cytokines related tissue repair, such as IL-10, IL-4, and IL-5, were also upregulated in COVID-19 patients, but without statistical significance between mild and severe patients." (PMID 32641700, 2020). "Indeed, elevated levels of IL-10, a TIGIT-signaling cytokine, have been documented in COVID-19 patients, suggesting that SARS-CoV-2 exploits these proteins to cover its molecular signatures." (PMID 32655579, 2020). "Moreover, the roles of anti-inflammatory cytokines in COVID-19 pathogenesis, including IL1R2, IL1RN, IL10, and TGFB1, are unclear and should be investigated in the future." (PMID 33101705, 2020). "Additionally, the levels of CD4+T and CD8+T and IL-6, IL-10, and NLR are potentially useful for predicting the development of COVID-19 and the severity of illness." (PMID 33134384, 2020). "Specially, an analysis on peripheral blood mononuclear cells from 14 patients in deteriorated condition from COVID-19 and 3 healthy controls revealed that COVID-19 patients have higher levels of both PD-1 and TIM-3 as well as remarkably elevated serum levels of IL-6, IL-10, and TNF-α." (PMID 32967229, 2020). "Reports also suggest that in certain instances, patients with severe COVID-19 were found to exhibit higher levels of pro-inflammatory cytokines such as IL-2R, IL-6, IL-8, IL-10, and TNF-α compared to patients with non-severe condition." (PMID 33120941, 2020). "Collectively, these findings suggested that IL-10 and TNF-α as immunosuppressive and pro-inflammatory agents, respectively,—might be prognostic and could serve as therapeutic targets for COVID-19." (PMID 33424804, 2020). "The phenomena suggests that the decrease of T cells seen in COVID-19 patients may be the result of high serum concentration of TNF-α, IL-6, and IL-10 negatively regulating T cell survival or proliferation." (PMID 32425950, 2020). "The cytokine storm landscape of COVID-19 patients was further demonstrated in a retrospective study showing higher concentrations of IL-2, IL-7, IL-10, G-CSF, C-X-C motif chemokine ligand (CXCL)-10, C-C motif chemokine ligand (CCL)-2, CCL-3, and TNF-α in the plasma of severe COVID-19 patients." (PMID 33584335, 2020). "As elevated serum levels of TIGIT and IL-10 have been documented in SARS-CoV-2 infection, the attenuated polio vaccine may be beneficial against COVID-19, as it inhibits CD155 and its immunosuppressive network." (PMID 32655579, 2020). "In our study, IL-10 production was elevated in the lungs of patients with COVID-19 and was found to be expressed by CD11b+ macrophages but not by CD11c+ DCs." (PMID 33424804, 2020). "We show that plasma CXCL2, CXCL10, CCL5, CD40 ligand, IL-10, and GM-CSF concentrations and ELF CXCL1, CXCL10, granzyme B, TRAIL, and EGF concentrations were found in greater concentrations in COVID-19 than in non-COVID-19 ARDS patients." (PMID 33138839, 2020). "Plasma from severe COVID-19 patients similarly exhibited increased IL-6, IL-10, and MCP-1 levels, but these levels were not as high as those in patients with CRS from other causes." (PMID 32826331, 2020). "Nevertheless, in COVID-19 patients, we observed higher IL-6:IL-10 and TNF-α:IL-10 ratios that could reflect an unbalanced overproduction of IL-10." (PMID 33272291, 2020). "Although IL-10 levels were significantly higher in COVID-19 patients with SP, patients with DHF had 25-fold higher levels, whereas IL-6 levels were 11-fold higher in those with COVID-19 SP." (PMID 33199778, 2020).
COVID-19 (continued). "In COVID-19 the homeostatic equilibrium between TREG cells (IL-10) and Th17 cells (IL-17) is broken: inflammatory cytokine levels (IL-1, TNF) are elevated in the lungs of COVID-19 patients, resulting in an increase in HA-synthase-2 (HAS2) in alveolar epithelial cells CD31+, EpCAM+ and fibroblasts." (PMID 33160363, 2020). "Previous studies have reported that the elevation in IL-6, IL-10, and IFN-γ levels in CRS, including CAR T cell therapy and severe COVID-19, is a typical phenomenon in HLH/MAS, wherein activated macrophages or T cells are the major producers of proinflammatory cytokines." (PMID 32826331, 2020). "However, we observed a more unbalanced inflammatory/anti-inflammatory cytokine response in COVID-19 patients, as reflected by the IL-6:IL-10 and TNF-α:IL-10 ratios." (PMID 33272291, 2020). "Indeed, patients with COVID-19 who displayed measurably higher levels of IP-10 (CXCL10), IL-10, and IL-6 when first admitted to hospital went on to become more severely ill." (PMID 33363221, 2020). "A retrospective study of 21 patients identified significant elevations of plasma IL-6, IL-10, TNFα and IL-2 receptor in severe (n = 11) compared to moderate (n = 10) cases of COVID-19, whereas IL-1β and IL-8 levels were not significantly different." (PMID 32629875, 2020). "Furthermore, seven core targets of VA against COVID-19, including MAPK1, IL10, EGFR, ICAM1, MAPK14, CAT, and PRKCB were identified." (PMID 32805728, 2020). "The stimulation of PBMCs from COVID-19 patients with S protein peptides resulted in production of effector or Th1 cytokines (IFN-γ, TNF-α, and IL-2) and, to a lesser extent, Th2 (IL-5, IL-13, IL-9, and IL-10) and Th17 (IL-17A, IL-17F, and IL-22) cytokines." (PMID 32916812, 2020). "Principle behind use: severe cases of COVID-19 are characterized by a cytokine storm defined as a sudden production of cytokines, such as IL-2, IL-7, IL-10, granulocyte colony-stimulating factor (G-CSF), MCP1, MIP-1a, and TNF-α, secondary to the upregulation of the inflammatory process in COVID-19." (PMID 32953365, 2020). "Clinical studies show that the levels of IL-2, TNF-α, IFN-γ, IP-10, MCP-1and other pro-inflammatory cytokines are significantly increased in severe or critical patients with COVID-19, while SARS-CoV-2 infection also increases secretion of anti-inflammatory cytokines (IL4 and IL10)." (PMID 32665783, 2020). "Another limitation is the limited number of cytokines analyzed, as only IL-6 and IL-10 were measured, which may not fully reflect the complexity of the immune-inflammatory response in COVID-19." (PMID 41203712, 2025). "This meta-analysis provides robust evidence that inflammatory biomarkers, particularly IL-6, IL-10, IL-8, and S100B, are significantly elevated in patients with COVID-19 pneumonia and organ failure compared to non-pneumonia COVID-19 patients and healthy controls." (PMID 41585373, 2025). "In this study, interestingly, mild/asymptomatic COVID-19+ pregnant women exhibited significantly elevated levels of proinflammatory cytokines/chemokines such as INF-α2, INF-γ, MCP-1, IL-6, IL-12p70, IL-17A, IL-18, IL-23, and IL-33, and the anti-inflammatory cytokine IL-10." (PMID 40303405, 2025). "This analysis showed that the Allele-1 group showed a significant effect of antibody response to COVID-19 vaccination both before and after vaccination in BMI values and, at the post-vaccination time point, in systemic levels of IL-17 and IFN-γ, and also in the ratios of IL-17/IL-10 and IFN-γ/IL-10." (PMID 40872872, 2025). "Studies have established that increased levels of IL-1β, IL-2, IL-6, IL-10, IFN-γ, TNF, IFN-γ-inducible protein 10 (IP-10), granulocyte macrophage-colony stimulating factor (GM-CSF), and monocyte chemoattractant protein-1 (MCP-1) correlate with COVID-19 severity." (PMID 39940907, 2025).
COVID-19 (continued). "In this sense, a meta-analysis carried out in 2020 that evaluated 8719 COVID-19 patients with severe disease found that those patients hospitalized in the ICU had elevated levels of acute phase reagents, such as erythrocyte sedimentation rate, CRP, IL-6, and IL-10, among others." (PMID 40756075, 2025). "In the COVID-19+ group, as expected, significantly increased levels of proinflammatory cytokines/chemokines including INF-α2, INF-γ, MCP-1, IL-6, IL-12p70, IL-17A, IL-18, IL-23 and IL-33 were detected, while the level of IL-10, an anti-inflammatory cytokine was also elevated as compared to controls." (PMID 40303405, 2025). "Furthermore, since IL-10 directly enlarges CD8+ T cells, hyperstimulation of adaptive immunity in COVID-19 patients may further worsen disease severity." (PMID 40143288, 2025). "Similarly, increased levels of interleukin-1 (IL-1), IL-6, IL-7, IL-10, tumor necrosis factor-alpha (TNF-α), and reduced expression of interferons (IFNs) have been associated with negative outcomes in individuals with COVID-19." (PMID 38601541, 2024). "Besides, a prediction model based on age, BMI, fever duration, leucocyte count, lymphocyte proportion, proportion of CD3+ T cells, TNF-α, and IL-10 was constructed and internally validated here, which showed a good performance for predicting severe H1N1 infection in the post-COVID-19 era." (PMID 38566022, 2024). "Similarly, a study conducted on patients with severe COVID-19 revealed that the levels of IL-2, IL-6, IL-10, and TNF-α were significantly higher compared to non-severe patients." (PMID 38355623, 2024). "Notably, certain gut bacteria that were depleted in COVID-19 patients, including Bifidobacterium adolescentis, Eubacterium rectale, and Faecalibacterium prausnitzii, negatively correlated with key inflammatory cytokines like CXCL10 and IL-10." (PMID 39518964, 2024). "As COVID-19 severity increased, there were corresponding rises in infection indicators like white blood cell (WBC) count, neutrophil to lymphocyte ratio (NLR), C-reactive protein (CRP), serum amyloid A (SAA), and inflammatory mediators such as interleukin-6 (IL-6) and interleukin-10 (IL-10)." (PMID 39081794, 2024). "Recently high titers of antibodies directed against IL-10 were shown to phenocopy the genetic disease, and this phenomenon is not unique to IL-10; other serum proteins can also serve as targets for an immune response, such as type I interferons in severe COVID-19." (PMID 39596040, 2024). "One of the objectives of our study was to molecularly and biologically evaluate the levels of pro-inflammatory cytokines (IL-1, IL-6) and anti-inflammatory cytokines (IL-4, IL-10) in the appendixes of children with COVID-19, considering the lack of data on this in the global literature." (PMID 38397914, 2024). "A binary logistic regression model was applied to our data regarding the COVID-19 patients with chronic CVD using statins and COVID-19 patients with no cardiovascular co-morbidities, with statistically significant differences in IL-6, TNFα, and IL-10 concentrations." (PMID 39518552, 2024). "Serum levels of IP10 and IL10 were higher at CT in COVID-19 cases compared with NAAT-ve participants, regardless of vaccine group (IP10: fdr = 0.026 compared to NAAT+ve ChAdOx1 nCoV-19 vaccinees and fdr = 0.0001 compared to NAAT+ve placebo vaccinees; fdr = 0.003 and 0.0006 for IL10, respectively)." (PMID 38649734, 2024). "The study identified IL-6, TNF, IL-1β, IL-10, and IL-2 as the five most distinctive cytokines that could effectively differentiate between individuals who had COVID-19 (including those with long COVID) and those who had never been exposed to the virus." (PMID 39518964, 2024).
COVID-19 (continued). "In the case of COVID-19, the cytokines involved in cytokine storm mainly include tumor necrosis factor-alpha (TNF-α), interleukin 1β (IL-1β), interleukin 6 (IL-6), interleukin 8 (IL-8), interleukin 10 (IL-10), interferon alpha (IFN-α), and granulocyte-macrophage colony-stimulating factor (GM-CSF)." (PMID 37841241, 2023). "However, T cells can not contribute to the high concentration of IL-10 because these patients are characterized by a marked lymphopenia, typical of COVID-19." (PMID 37187739, 2023). "In this regard, it has been reported that post-COVID-19 patients develop a cytokine syndrome characterized by an imbalance of pro-inflammatory and anti-inflammatory cytokines, such as IL-17 and IL-2, and IL-10 and IL-4, compared with COVID-19 patients without sequelae." (PMID 36836568, 2023). "Moreover, most of these correlations were lost in critical COVID-19 patients except the negative correlation of IL-6 with leptin levels, and positive correlations found between IL-10 and TNFα and Resistin." (PMID 36509969, 2023). "Moreover, higher serum levels of IL-10 were found in individuals who did not experience sequelae after acute infection compared to subjects with post-COVID-19." (PMID 37359549, 2023). "Apart from periodontitis and COVID-19, local (salivary) and systemic (serum) TNF-α/IL-6/IL-1β levels also increased in other inflammatory conditions, such as chronic oral erosive lesions and ulcers, and these cytokine levels were inversely proportional to the IL-10 that regulated epithelial healing." (PMID 37106750, 2023). "Previous studies found that thymosin drugs could inhibit the inflammatory/activated state of monocytes in the treatment of COVID-19 by reducing the release of proinflammatory mediators such as TNF-α, IL-6 and IL-8, and promote the generation of anti-inflammatory cytokines such as IL-10." (PMID 37743481, 2023). "Finally, COVID-19 hyper-inflammatory patients had higher levels of MIP-1β, IL-10, and IP-10." (PMID 36814234, 2023). "Patients in the ICU with COVID-19 have higher peripheral IL-10 levels than those in non-ICUs." (PMID 38249419, 2023). "Importantly, the combination of serum levels of IL-10, IL-23 and TNF-α were strongly linked with non-survivors in COVID-19 patients." (PMID 37283736, 2023). "It was shown that targets of the drug combinations (including TNF, IL1B, IL10, and CCL2) (p=5.72×10−5) and, specifically, its individual drugs including EH (p = 0.00142), PR (p=4.37×10−4), and GR (p=5.81×10−5) are significantly overlapped with COVID-19-related genes obtained from the CTD database." (PMID 36611603, 2023). "Patients in stage IV of COVID-19 had significantly higher serum level of pro-inflammatory cytokines IL-1β (p = 0.001), TNF-α (p = 0.012) and IL-12 (p = 0.001) as well as immunosuppressive IL-10 (p = 0.001) compared to the patients in less severe stages of disease." (PMID 36702907, 2023). "In severe COVID-19, higher RBD-specific IgG4 levels were noted in deceased individuals than survivors, potentially due to cytokine storms including both anti- and pro-inflammatory cytokines, including IL-10, which could further driving IgG4 induction." (PMID 38173725, 2023). "Accordingly, in the scenario of COVID-19, IL-10 might worsen the disease outcome rather than produce a benefit." (PMID 36035415, 2022). "In ICU patients with COVID-19, the quantity of Tregs in PBMCs and their functional molecules (TGF-β and IL-10) were significantly reduced, accompanied by an increased ratio of Th17/Treg cells, RORγt/FoxP3, and IL‐17/IL‐10 in patients compared with the controls." (PMID 36505489, 2022). "Although implemented studies have shown that plasma IL-6 and IL-10 could be used as factors to predict the progression of COVID-19, their values could not be used separately to distinguish COVID-19 stage groups." (PMID 36438922, 2022). "Similarly, a total of 10 eligible studies were used for pairwise comparison between survivor and non-survivor COVID-19 cases for IL-10." (PMID 35572964, 2022).